CAT (catalase)
Diseases named in the same sentence as CAT in open-access papers (continued):
Sharing a sentence is not in itself a finding about the gene and the disease.
tumor (continued). "In this system, the Au@ZIF-8 utilized its catalase potential by catalyzing the high hydrogen peroxide expressed in the TME to produce oxygen to alleviate tumor hypoxia, increasing ROS production with strong cytotoxicity and tumor cell death." (PMID 36230480, 2022). "The single ruthenium atom (active catalytic site) duplicated the action of the enzyme CAT that led to higher oxygen production for relieving tumor hypoxia and thus promoting PDT of cancer." (PMID 35740402, 2022). "PPA2, a serine/threonine phosphatase, acts as an inducer of apoptosis and as a human tumor suppressor and has been described to decrease CAT activity." (PMID 36555526, 2022). "The phenomenon of increased SOD2 levels and decreased CAT levels has previously been observed in tumor cells from advanced stages of disease and has been shown to promote tumor cell proliferation and invasive and migratory phenotypes." (PMID 36264639, 2022). "It has been shown that MnO2-based nanomaterials display CAT-mimic catalytic activity to decompose H2O2 in the tumor site to form O2, thus alleviating the tumor hypoxia 20-25." (PMID 35547775, 2022). "As expected, H2O2 levels was substantially reduced by catalase in crude lung samples isolated from tumor-bearing mice." (PMID 35126389, 2022). "Among the catalysts, catalase (CAT) from the bovine liver can effectively convert H2O2 to O2 in the tumor site." (PMID 35387175, 2022). "Under acidic circumstances, the produced H2O2 from MO2 reacting with H2O not only causes oxidative stress but also generates additional O2 by serving as a reaction substrate for molecules like CAT or MnO2 to reduce tumor hypoxia and reverse TME." (PMID 36568636, 2022). "BSNSs-CAT + RT had the best tumor growth inhibition effect thanks to the strong reflective absorption of Bi and the improvement of the hypoxic microenvironment, followed by BSNSs + RT, then RT group." (PMID 35250594, 2022). "In another similar study, a tumor-targeted cascade bioreactor with encapsulations of Gox and CAT in cancer cell membrane-camouflaged porphyrin metal–organic framework (MOF) was developed for synergistic action of enzyme-mediated starvation therapy and PDT." (PMID 35119544, 2022). "In another study performed by Hei and collaborators, catalase was also incorporated in liposomes, to overcome tumor hypoxia, presenting at their surface a programmed death ligand 1 monoclonal antibody to enhance immunotherapeutic effects towards melanoma." (PMID 35335906, 2022). "As expected, the catalytic effect of CAT increased intracellular O2 content of tumor cells, and then a large number of ROS induced by Ce6 was produced under 660 nm NIR, thus effectively enhancing the immunotherapeutic efficacy of PDIT." (PMID 35910806, 2022). "After local injection of BFV, PAI was used to determine tumor sO2, and it was found that sO2 levels of BFV-treated tumor were comparable to CAT-only treated tumor." (PMID 35624636, 2022). "The expressed catalase in engineered M1Exos led to the relief of tumor hypoxia, and the small‐molecular inhibitor loaded in engineered M1Exos caused the inhibition of DNA damage repair." (PMID 35715382, 2022). "Such catalytic oxygenation can be achieved by catalase and some catalase-mimic nanozymes, which possesses the advantages of high efficiency, tumor specificity, and constant oxygen generation." (PMID 36109814, 2022). "CAT can efficiently reoxygenate the hypoxic tumor via converting endogenous H2O2 into O2 to enhance the curative effect of PDT." (PMID 35119544, 2022). "Then, ROS generation and deep tumor penetration can be achieved under ultrasonic treatment to effectively generate ROS as oxygen is sustainably supplied by catalase activity that decomposes endogenous H2O2 into molecular oxygen." (PMID 36531004, 2022).
tumor (continued). "Catalase in the core of the nanoplatform decomposed H2O2 to produce O2 in the tumor microenvironment to relieve hypoxia, directly reducing hypoxia‐inducible factor‐1α (HIF‐1α) expression and indirectly down‐regulating the expression of PD‐L1." (PMID 35652198, 2022). "MnO2 nanoparticles with tumor microenvironment-responsive degradation characteristics and catalase properties can react with excess H2O2 present in tumor tissue, producing O2 and Mn2+ to alleviate tumor hypoxia." (PMID 36177188, 2022). "On the other hand Cs, particularly its fluorinated derivative (FC), can be used for enhanced mucoadhesion of NPs and deep tumor cell penetration by coupling FC to sonosensitizer-conjugated catalase post-intravesical instillation." (PMID 36531004, 2022). "Meanwhile, CAT encapsulated in nanoparticles decomposed H2O2 into oxygen for overcoming tumor hypoxia and further enhancing PDT efficacy." (PMID 35119544, 2022). "So, the depleted levels of GSH and catalase as a result of CMF therapy in tumor animals (p < 0.01) was restored by all the treatment groups but more significantly by the Mulmina treatment, MN-40 (p < 0.01) and MN-80 (p < 0.001)." (PMID 35197512, 2022). "This co-delivery system significantly improved PDT efficacy by CAT catalysis-mediated alleviation of tumor hypoxia and CTPP-mediated mitochondria targeting upon irradiation using 980 nm laser." (PMID 36147526, 2022). "Catalase is chosen to react with hydrogen peroxide overproduced in the tumor microenvironment (TME) to generate oxygen in situ to improve tumor hypoxia for enhanced SDT." (PMID 34989170, 2022). "Thirdly, the isolated overexpression of CAT in experiments led to the prevention of malignant transformation or to the suppression of tumor cells growth significantly more frequently than it did to cancer promotion." (PMID 36552527, 2022). "Recently, researchers have developed versatile ROS-responsive nanoparticles through catalase (CAT)-mediated tumor site-specific O2 generation to alleviate hypoxia for enhancing tumor treatment." (PMID 36096856, 2022). "Several researchers have reported the synthesis of transferrin-modified MgO2 nanosheets (TMNSs), which have a similar reaction to the neutral pH and low CAT activity of the tumor microenvironment." (PMID 36568636, 2022). "Normalization of tumor extracellular pH using bicarbonate or oxygen-generating catalase during TACE counteracted these immunosuppressive effects and triggered the homing of the cytotoxic lymphocytes, resulting in tumor regression." (PMID 35619923, 2022). "And fortunately, diverse nanozymes that mimic natural enzyme capabilities have been extensively investigated and validated to be prospective alternatives to the scant autologous catalase in the tumor location." (PMID 35413839, 2022). "Catalase can catalyze the in situ production of O2 to relieve the hypoxic tumor microenvironment, and antisense DNA can downregulate HIF-1α to enhance PDT efficacy." (PMID 34168817, 2021). "Over-expressed H2O2 is produced by the abnormal metabolism of tumor cells, while, targeting CAT to decompose H2O2 will accelerate the abnormal metabolism of tumor cells remains to be researched." (PMID 34277702, 2021). "The addition of H2O2 to tumor cells produced the same cell death effect as that caused by AA, while simultaneous use of the antioxidants N-acetylcysteine or catalase with AA inhibited AA-induced tumor cell death." (PMID 34504430, 2021). "CAT can catalyze H2O2 overexpressed in the tumor microenvironment to generate oxygen, alleviate tumor hypoxia, and synergistically improve radiotherapy efficacy." (PMID 35011360, 2021). "Therapy using catalase for inhibiting tumor growth has been implemented and a recombinant catalase has been used as immunomodulator for fighting H1N1 pneumonia." (PMID 34458243, 2021).
tumor (continued). "Attractively, the by-product, H2O2 during the glucose oxidation by GOD, provides sufficient reactant for the O2 generation under the catalysis of CAT and, more importantly, relieves tumor hypoxia for promoting SDT-mediated 1O2 generation." (PMID 34195614, 2021). "One is based on catalase grafting to achieve oxygen self-sufficient NPs in order to convert H2O2 into available dissolved oxygen in the tumor environment." (PMID 34959277, 2021). "Innovative MnO2 nanoparticles (NPs) act as catalase in low-pH tumor microenvironments, leading to a reduced hypoxic state." (PMID 34395406, 2021). "More importantly, the infiltration of CAT-mimic in tumor tissues has the capability of activating the matrix metalloproteinases, which can cause inflammation and promote tumor metastasis." (PMID 34277702, 2021). "High expression of catalase (CAT), which is overexpressed in the tumor microenvironment, can convert H2O2 into oxygen, relieving hypoxia and weaking the anticancer effect of TPZ." (PMID 34949202, 2021). "In qRT-PCR, catalase showed a significant upregulation in tumor tissue in comparison to control tissue." (PMID 34360635, 2021). "The tumor levels of catalase increased by 161.11% (p < 0.001) in animals treated with tamoxifen, as compared to the DMBA + DW control group." (PMID 34367310, 2021). "Catalase encapsulated in the in situ hybrid hydrogel triggers endogenous hydrogen peroxide decomposition to produce oxygen, which continuously alleviates tumor hypoxia." (PMID 34842684, 2021). "Multifunctional immunoliposome CAT@aPDL1-SSL delivers the oxygen generating enzyme—catalase to the hypoxic regions of the tumor and reduces the extracellular acidity." (PMID 33918883, 2021). "Nanoenzyme, who can mimic the activity of natural catalase, has been widely integrated with nanoagents for oxygen-evolving therapy by catalyzing the decomposition of hydrogen peroxide in tumor microenvironment." (PMID 33407506, 2021). "O2 self-produced nanoplatforms, such as manganese dioxide (MnO2) nanoparticles and catalase-loaded nanoparticles triggered by unique tumor microenvironment (i." (PMID 33408790, 2021). "As a photothermal agent, Prussian blue (PB) nanozyme can stimulate the disintegration of the hydrogel while also acting as a catalase (CAT) enzyme to catalyze H2O2 to improve the tumor microenvironment." (PMID 34881231, 2021). "Catalase can significantly reduce the invasive behavior of tumor cells in a transgenic mouse model of metastatic breast cancer (MMTV-PyMT)." (PMID 34476214, 2021). "Here the authors design a nanoprobe based on NIR-IIb emitting quantum dots for image-guided RT and modified with catalase to relieve hypoxia in the tumor microenvironment, enhancing the precision and efficacy of RT and promoting anti-tumor immune responses." (PMID 34887404, 2021). "At the same time, Mn element renders the LMM@BSA clay nanosheets the tumor reducibility and acidity responsive MR imaging and catalase-mimic capacities to catalyze the disproportionation of H2O2." (PMID 33536031, 2021). "It is predictable that varying degrees of NOX1, catalase, aquaporin, xCT, glutathione synthase and glutathione peroxidase expression can be expected in different tumor cell lines." (PMID 34679719, 2021). "Although promising in anti-inflammatory, tumor treatment, biological detection and many other fields, considerable CAT mimics still constrained by the obscure mechanism." (PMID 34241715, 2021). "Once enter the tumor site, the concentration of these NPs would be gradually decreased to trigger their dissociation into smaller CAT-based NPs, thereby enabling enhanced penetration inside the tumor and effectively decomposing H2O2 into oxygen." (PMID 34277702, 2021). "In a phase I trial where P-AscH− was included as an adjuvant to the standard of care, short-term survivors had higher catalase levels in tumor tissue, compared to long-term survivors." (PMID 33923601, 2021).
tumor (continued). "Catalase can catalyze the breakdown of hydrogen peroxide and thus improve the tumor microenvironment." (PMID 34395406, 2021). "Our analysis revealed that the mRNA levels of NQO1 were significantly elevated (p = 1.5×10-7), while CAT levels were notably lower (p = 7.8×10-8) in tumor tissues than in matched normal tissues." (PMID 34676172, 2021). "Several lines of studies suggest that SP decreased ROS production through induced catalase gene expression, resulting in enhanced proliferation of tumor cells and decreased apoptosis." (PMID 33976938, 2021). "The authors found that tumor cells always had low MnSOD activity, typically low CuZnSOD activity, and almost always low CAT activity compared with matching normal tissues." (PMID 34285315, 2021). "With some protective catalase molecules inactivated in these tumour cells, the surviving cell-derived, extracellular H2O2 and ONOO− form secondary 1O2." (PMID 33801451, 2021). "This interaction bears a chance for synergistic effects during tumor therapy, based on interactive glutathione depletion and catalase inhibition." (PMID 34679719, 2021). "With this regard, various CAT-based NCs have been developed to retain its catalytic activity during the tumor-targeted delivery process." (PMID 34277702, 2021). "CAT was detected in all tumor tissue samples with different staining score: 2 out of 15 (13.3%) were weakly positive, 11 out of 15 (73.3%) were positive, and 2 out of 15 (13.3%) were strongly positive." (PMID 34320944, 2021). "As a photothermal agent, Prussian blue (PB) nanozyme stimulates the disintegration of the hydrogel while also stimulating CAT to scavenge H2O2 to sensitize the tumor microenvironment." (PMID 34746011, 2021). "The results indicated that antioxidant molecules, including MnSOD and catalase, were upregulated and activated as an adaptive response to maintain tumor cell survival." (PMID 34692691, 2021). "Huang and colleagues reported the synthesis of dendritic mesoporous organosilica NPs encapsulating ICG and catalase (ICG-CAT@MONs) to overcome the tumor hypoxia induced PDT limitation and PA/US-guided tumor ablation." (PMID 34522227, 2021). "Consistently, markedly higher NQO1:CAT ratios were observed in these tumor samples than in normal samples (p = 1.5×10-9)." (PMID 34676172, 2021). "When internalized by tumor cells, the CAT‐imprinted nanoMIP selectively recognized and captured CAT molecules, inducing intracellular accumulation of H2O2, one of the major reactive oxygen species (ROS)." (PMID 32789971, 2021). "Due to the overexpressed H2O2 in tumor (100 μM–1 mM), various natural enzymes (catalase) and metals or metal-oxide based nanozymes have been applied to overcome tumor hypoxia by catalyzing the in situ transformation of endogenous H2O2 to O2." (PMID 33954158, 2021). "Consistently, our western blotting analysis revealed that NQO1 protein levels were obviously elevated in 43.8% (28/64) of HCC tumor tissues, while catalase levels were repressed significantly in most HCC tumor tissues." (PMID 34676172, 2021). "Immature myeloid cells differentiated into macrophages when H2O2 was scavenged with catalase, while deficiency of NOX activity caused MDSCs to differentiate into macrophages and DCs in tumor-bearing mice." (PMID 32630174, 2020). "CAT activity was also higher in patients with moderate and strong inflammatory infiltration both in the front of the tumour and in tumour centre than in weak infiltration." (PMID 32575703, 2020). "They increased the oxygen content of the tumor microenvironment by loading reactive oxygen species and catalase on the MOFs, improving the efficiency of photodynamic therapy while achieving starvation therapy." (PMID 32151012, 2020). "In another study, targeted transportation of a catalase-loaded nanocarrier to the tumor site catalyzing the high content of H2O2 in cells to increase the supply of oxygen was also an effective way to improve the therapeutic effect." (PMID 31903156, 2020).
tumor (continued). "The catalase activity was found to be stronger in the surrounding as compared to the tumor with exceptional, where tumors had strong catalase activity (Catalase)." (PMID 32158360, 2020). "Further research should be conducted to maximize the efficacy of PAA-TiOxNPs through a combination with catalase inhibitors or by actively targeting tumor tissues by combining with targeted therapy." (PMID 32517328, 2020). "Higher tumor accumulation and complete inhibition of tumor growth was observed for the catalase and targeting moiety containing formulation, while other approaches led to tumor growth within 8 days post-treatment." (PMID 33202648, 2020). "Based on this strategy, they prepared a catalytic nanoreactor by loading catalase into mesoporous organic silica nanoparticles (catalase@MONs) for tumor-targeted delivery and controlled generation of O2." (PMID 34691545, 2020). "Our findings showed a significant reduction in GPx and catalase activities and an enhancement in all tissue values in the Tumor Control group, but which were reversed approximately in the control levels in the groups." (PMID 32986349, 2020). "This is because tumor cells have a high local concentration of catalase on cell surface that protects them against exogenous H2O2 and peroxynitrite." (PMID 33202842, 2020). "When intracellular H2O2 penetrates into the skeleton, it was catalyzed by CAT to produce O2 at the hypoxic tumor site, thereby promoting the production of toxic 1O2." (PMID 33343807, 2020). "Encapsulation of the nanoparticles in RBC membranes not only prolonged the circulation time of the probe but also catalyzed endogenous H2O2 by the catalase in RBCs to ameliorate tumor hypoxia." (PMID 31903156, 2020). "In recent years, many studies have reported that various nanoplatforms, such as perfluorocarbons 134, hemoglobin 135, catalase 136, and manganese dioxide derivatives 137, 138, delivered oxygen to tumor sites to overcome anoxic environments." (PMID 32641993, 2020). "Catalase (CAT, ctl-1 and ctl-2) has the function of regulating host defense to pathogens, apoptosis, aging, inflammation, tumor formation, and mutagenesis." (PMID 32337270, 2020). "The catalase and photosensitizer-loaded hybrid nanoparticles show enhanced retention in tumor tissue, leading to greatly relieved tumor hypoxia via decomposition of tumor endogenous H2O2 and improving anti-PD-L1 checkpoint blockade therapy." (PMID 32824578, 2020). "Illustratively, the PS methylene blue (MB) and a catalase (CAT) were simultaneously delivered into tumor cells via their encapsulation in ZIF-8-gated PDA nano-carrier." (PMID 33212974, 2020). "Inspired by HUVECs targeting and catalase overcoming hypoxia in cancer cells, the in vivo distribution and tumor accumulation of Dir-labeled nanoparticles were studied." (PMID 33240803, 2020). "Ex vivo organ imaging also revealed that after PDT, the accumulation of ENPs in tumor tissues was 3.6-fold higher than that of NPs and increased to 12-fold after catalase encapsulation." (PMID 33240803, 2020). "The shell was modified with catalase (E), which catalyzes the conversion of hydrogen peroxide to oxygen at the tumor site, alleviating hypoxia and increasing the effect of the photodynamic treatment." (PMID 31534494, 2019). "As a consequence of primary 1O2, local inactivation of membrane-associated catalase is achieved and leads to the sustained generation of secondary singlet oxygen, starting with the interaction between H2O2 and ONOO− generated by the tumor cells." (PMID 31558835, 2019). "Attempts to identify the mechanism of neutrophil killing of tumor cells in these studies pointed to a role of hydrogen peroxide (H2O2) since catalase significantly reduced the extent of tumor cell lysis." (PMID 31379875, 2019).